KIR2DL4 (killer cell immunoglobulin like receptor, two Ig domains and long cytoplasmic tail 4)
Diseases named in the same sentence as KIR2DL4 in open-access papers (continued):
Sharing a sentence is not in itself a finding about the gene and the disease.
cancer (16 papers, 2019 to 2025). A tumor composed of atypical neoplastic, often pleomorphic cells that invade other tissues. "KIR2DL4 has been implicated in cancer in relationship to the immune microenviroment and is subject to evolving mangement avenues for targeted cancer immunotherapy." (PMID 37892181, 2023). "It has been reported that KIR2DL4 was highly associated with cancer development, and its lower expression level means better prognosis." (PMID 36003401, 2022). "The long-term outlook for KIR2DL4 targeted cancer immunotherapy is promising but also faces challenges." (PMID 40549069, 2025). "In this review, we aim to summarize and discuss the potential role of KIR2DL4 as a target for cancer immunotherapy." (PMID 40549069, 2025). "In HLA-G-negative tumors, KIR2DL4 promotes ADCC through an IFN-γ-mediated feedback circuit until IFN-γ eventually upregulates PD-L1 on cancer cells." (PMID 36261539, 2023). "Accumulating evidence has shown that HLA-G is an immune checkpoint molecule with specific relevance in cancer immune escape, although the role of HLA-G/KIR2DL4 in antitumor immunity is still uncharacterized." (PMID 35185887, 2022). "Herein, we then focused on the interaction of human mast cells expressing KIR2DL4 with HLA-G-positive trophoblasts during pregnancy establishment and with HLA-G-positive cancer cells during cancer progression." (PMID 32023940, 2020). "Coexpression of HLA-G and KIR2DL4 therefore worsens cancer prognosis by mediating cancer invasion and metastatic spread, as has been reported in breast cancer." (PMID 31013867, 2019). "Deeply understanding the functions and interactions of KIR2DL4 may lead to the development of more effective immunotherapy strategies that harness the immune system against cancer cells." (PMID 40549069, 2025). "All these studies showed that KIR2DL4 plays an important role in cancer immunotherapy and targeting KIR2DL4 might be an effective approach." (PMID 40549069, 2025). "A better understanding of KIR2DL4 might be helpful to develop effective KIR2DL4-targeted therapies, which could provide new treatment options for cancer patients." (PMID 40549069, 2025). "Additionally, with the advancement of technologies for KIR2DL4 modulation, such as gene editing and novel imaging techniques, the future of KIR2DL4-targeted cancer immunotherapy looks promising." (PMID 40549069, 2025). "If the challenges related to specificity, efficacy, and side effects can be addressed, KIR2DL4 targeted therapies could become an important part of the cancer treatment arsenal." (PMID 40549069, 2025). "With the unique structure, whether KIR2DL4 participates in cancer immunotherapy remains to be explored." (PMID 35185887, 2022). "Moreover, KIR2DL4 as a receptor on HLA-G, has been thought as one of potential targets for immunotherapy to treat cancer." (PMID 35345444, 2022). "However, there are a series of KIRs based immunotherapy strategies that can provide new insights into future cancer immunotherapies targeting KIR2DL4, such as immune checkpoint blockade (ICB) therapy, adoptive cell transfer (ACT) therapy and small-molecule inhibitors." (PMID 40549069, 2025). "Therefore, interfering with HLA-G/KIR2DL4 signaling combined with PD-L1/PD-1 targeting may potentiate trastuzumab treatment in those resistant cancers." (PMID 36261539, 2023). "According to some reports, KIR2DL4 may be an intervention for cancer immunotherapy." (PMID 34660598, 2021). "However, KIR2DL4-targeted drugs might enhance HLA-G-positive cancer progression, and patients treated with KIR2DL4 stimulants should first be carefully screened for the presence of malignancy." (PMID 32023940, 2020). "Thus, KIR2DL4 on mast cells seems to be involved in cancer progression." (PMID 32023940, 2020). "(M-Q) Phenotype switch (KIR2DL4, GZMK, CD9, CD49a, and PD-1) of NK cells was induced by cell-to-cell interactions with cancer cells." (PMID 39387546, 2024).
cancer (continued). "Analysis of data from The Cancer Genome Atlas and Genotype‐Tissue Expression databases revealed that KIR2DL1, KIR2DL3 and KIR2DL4 expression were significantly upregulated in AML and associated with decreased overall survival (OS)." (PMID 38527290, 2024). "Cancer cells may upregulate expression of the human leukocyte antigen-G (HLA-G), which interacts with inhibitory receptors on immune cells, such as ILT2 and KIR2DL4, to suppress immune responses." (PMID 39040441, 2024). "However, there are no efficient cancer immunotherapy strategy targeting KIR2DL4." (PMID 40549069, 2025).
KIR2DL4 also shares sentences with these, for which no sentence is quoted: infection (7 papers); ovarian carcinoma (2); autoimmune disease (1); cutaneous mastocytosis (1); Diabetes (1); gastric cancer (1); gastroenteritis (1); Langerhans cell histiocytosis (1); lung carcinoma (1); metastasis (1); neurological diseases (1); Type 1 diabetes (1).